EZH2 (enhancer of zeste 2 polycomb repressive complex 2 subunit)
Diseases named in the same sentence as EZH2 in open-access papers (continued):
Sharing a sentence is not in itself a finding about the gene and the disease.
tumor (continued). "EZH2 (e.g., tazemetostat) and BET (e.g., JQ1) inhibitors reverse immune exclusion by reactivating silenced tumor-suppressor genes (e.g., HLA class I) and chemokine production." (PMID 40661151, 2025). "Conversely, pharmacological inhibition of EZH2 restores MHC-I expression, reactivates antitumor immunity, and suppresses tumor growth." (PMID 41353272, 2025). "Similar to EZH2, JMJD3 also exhibits a dual role in tumorigenesis, with its tumor-promoting or suppressive effects influenced by the environmental and genetic characteristics of tumor cells." (PMID 40042761, 2025). "In the context of bone metastasis, EZH2 promotes osteolytic lesion development by upregulating integrin β1 and activating FAK–TGF-β signaling, thus enhancing osteoclast differentiation and tumor growth within the skeletal niche." (PMID 40872531, 2025). "This subtype exhibited significant stem cell-like characteristics, marked by the high expression of key stemness genes such as EZH2, LGR5, NOTCH1, and ABCG2, which together formed a core regulatory network maintaining tumor stem cell properties." (PMID 40787449, 2025). "Daily oral administration of HOC in a nude mouse NEPC xenograft model markedly suppressed the tumor expression of EPHA3 and BRN2, along with their downstream effectors EZH2, ASCL1, and DLL3 and neuroendocrine markers SYP and CHGA." (PMID 41514539, 2025). "Key enzymes like EZH2, BMI1, KMT1A, and EHMTs repress tumor-suppressor genes and maintain a proliferative, undifferentiated state." (PMID 40508013, 2025). "Immunohistochemistry (IHC) staining in 20 pairs of HNSCC samples revealed that elevated levels of EZH2 and MYC were present in tumor tissues than adjacent normal tissues." (PMID 39823459, 2025). "By interfering with the activity of HMTs such as G9a and EZH2, EGCG reduces histone methylation and helps reactivate silenced tumor-suppressor genes, providing another valuable avenue for cancer therapy." (PMID 41335282, 2025). "Tumor-infiltrating Treg cells have significantly high levels of H3K27 and EZH2, triggering immunosuppressive environments, and CCR6-CCL20 pathways produce Th17 cells that complicate the prognosis." (PMID 39996755, 2025). "EZH2 knockdown markedly reduced CRC cell proliferation, while its overexpression promoted tumor growth and increased resistance to irinotecan." (PMID 40314246, 2025). "EZH2-mediated H3K27me3 repression of anti-fibrotic genes leads to a fibrotic, desmoplastic TME, supporting tumor survival." (PMID 40299416, 2025). "The EZH2/PRC2|miR-3189|COL6A2 axis drives EMT and tumor progression, highlighting its potential as a therapeutic target in GBM." (PMID 40565099, 2025). "EZH2 and EED were predominantly localized to the nucleus in tumor cells, consistent with their known roles in chromatin modification." (PMID 40766612, 2025). "The NEAT1-EZH2/DNMT1 axis functions through NEAT1 binding to EZH2 or DNMT1, leading to silencing of p21 and DUSP4 by H3K27me3 or DNA methylation, facilitating tumor immune evasion and chemotherapy resistance." (PMID 41394878, 2025). "Our results showed that EZH2 inhibition restored Perforin+ CD8+ T cell populations, indicating enhanced functional cytotoxic activity against CRPR2 tumor cells." (PMID 41353272, 2025). "Blocking the recruitment of EZH2 upregulated the tumor suppressors PTENP1 and PTEN contributing to the reduction in breast cancer cell proliferation and tumor growth seen in xenograft mouse models." (PMID 41327312, 2025). "MiR-101 acts as tumor suppressor in lung and breast cancer, by negatively regulating DNMT3A and EZH2; miR-193 targets DNMT3A and HDAC in acute myeloid leukemia cells." (PMID 41595461, 2025). "This drives tumor progression and resistance to irinotecan, with NRP1 knockdown partially reversing the effects of EZH2 overexpression on both cell proliferation and autophagy suppression." (PMID 40314246, 2025).
tumor (continued). "EZH2 and EED act as downstream regulators of this pathway, with phosphorylated E2F binding to the EZH2 and EED promoters, disrupting the tumor cell cycle and driving malignant progression." (PMID 40042761, 2025). "In contrast, squamocin demonstrates a more pronounced suppression of tumor growth both in vitro and in vivo, exerting significant inhibition on H3K27me3 and MYC, which represent the enzymatic and non‐catalytic functions of EZH2, respectively." (PMID 39823459, 2025). "Conversely, HBx recruits histone methyltransferases like EZH2 and SUV39H1 to introduce repressive marks (H3K27me3 and H3K9me3), silencing key tumor suppressor genes." (PMID 40589575, 2025). "In tumors, EZH1 is able to partially compensate for the function of EZH2, maintaining the methyltransferase activity of PRC2, and thereby regulating the plasticity and heterogeneity of tumor cells." (PMID 41338460, 2025). "Our findings revealed that EZH2, AURKA, BID, PLA2G6, and EPAS1 exhibited significantly elevated expression levels in ccRCC tumor tissues compared to normal tissues." (PMID 40271062, 2025). "In conclusion, sICOSL-blockade therapy, including EZH2 and ADAM10/17 inhibitors, enhanced T cell cytotoxicity, delayed tumor progression and enhanced tumors response to chemoimmunotherapy." (PMID 40708008, 2025). "Specific methyltransferases such as EZH2, EHMT1/2, and KMT1A, and demethylases including KDM3A/B and KDM4B, form oncogenic axes that sustain tumor growth and block myogenesis." (PMID 40508013, 2025). "Specifically, EZH2 inhibition upregulates TAP1, restores MHC I expression on the tumor cell surface, and increases the presentation of antigenic peptides, making the tumor more likely to be recognized and targeted by the immune system." (PMID 41220942, 2025). "EZH2 inhibition was found to activate the immune response by upregulating MHC class II and other immune genes in the tumor microenvironment, effectively reversing an epigenetically enforced immunosuppressive state." (PMID 40918525, 2025). "EZH2 was primarily located in monocyte/macrophage cells, whereas the expression of AK5 was detected in fibroblasts, epithelial cells, and tumor cells." (PMID 40161494, 2025). "EZH2 directly regulates neuropilin-1 (NRP1) expression, driving tumor growth and resistance to irinotecan." (PMID 40314246, 2025). "EZH2 interacts with oncogenes (MYC, PTEN) to influence tumor malignancy by activating the EMT mechanism, initiating GBM cell invasion and metastasis." (PMID 40725030, 2025). "Next-generation approaches currently prioritize covalent EZH2 inhibitors and dual EZH2/HDAC degraders to overcome compensatory resistance mechanisms, although tumor-selective delivery remains a critical translational barrier." (PMID 40787450, 2025). "Enhancer of zeste homolog 2 (EZH2), a PRC2 component, is increasingly expressed from normal tissue to IDC, indicating its role in tumor aggressiveness." (PMID 40563575, 2025). "Specifically, elevated levels of EZH2 in CRC tissues and cells promote tumor cell proliferation and chemoresistance to irinotecan by suppressing autophagy." (PMID 40314246, 2025). "Thyroid hormone-mediated EZH2 inhibition reduces H3K27me3 histone marks at NEUROD1 regulatory regions and enhances NEUROD1 expression, eventually driving tumor cell differentiation into postmitotic cells and suppressing MB growth irreversibly." (PMID 40599851, 2025). "This aligns with the observation that EZH2 epigenetically regulates the expression of VASH1 and controls tumor angiogenesis in various types of cancer, demonstrating promising role of EZH2 inhibitors in various disease." (PMID 39934895, 2025). "E7 recruits HDAC1/2 and EZH2, the methyltransferase component of PRC2, promoting repressive H3K27me3 marks on tumor suppressors​." (PMID 40557320, 2025). "Given that increased activity of STAT3, NF-κB, EZH2, and HDAC3 has also been reported in other tumors, it will be interesting to investigate the role of IκBζ in additional tumor entities." (PMID 40562773, 2025).
tumor (continued). "To further explore the potential involvement of EZH2 in tumor-immune interactions, we employed the TIMER database to assess correlations between EZH2 expression and immune cell infiltration in HCC." (PMID 41209556, 2025). "The gene expression analysis revealed that several hub genes, such as ETNK1, KDM3A, EZH2, SMARCA4, and CASP3, were significantly overexpressed in HCC tissues, suggesting their potential roles in tumor progression and as biomarkers for HCC." (PMID 40074445, 2025). "GSK126, an EZH2 inhibitor, induced MDSC production and suppressed T-cell-mediated tumor immunity, masking its tumor-suppressing effects." (PMID 40042761, 2025). "Recent studies indicate that EZH2, through its interaction with pathways such as STAT3, contributes to immune evasion by upregulating PD-L1 expression, which facilitates tumor progression." (PMID 40038276, 2025). "To investigate the anti-tumor efficacy of targeting EZH2 in TCL, we conducted a cell viability assay on tumor cell lines treated with the EZH1/2 inhibitor Valemetostat, the EZH2 PROTAC degrader MS177, the EZH2 inhibitor EPZ6438 and SHR2554." (PMID 40659662, 2025). "Like DKO results, EZH2 and PI3K/mTORC1 inhibitor combination plus castration or enzalutamide provided most significant anti-tumor activity." (PMID 40832297, 2025). "EZH2 is a histone methyltransferase and core member of the PRC2 complex, which promotes tumor progression via widespread epigenetic silencing of tumor suppressor genes." (PMID 41470046, 2025). "EZH2, the catalytic subunit of PRC2, silences genes through histone H3 lysine 27 trimethylation (H3K27me3), affecting over 200 tumour suppressor genes." (PMID 40070134, 2025). "Liquid biopsies: Circulating tumor DNA (ctDNA) from plasma or cerebrospinal fluid (CSF) can detect epigenetic changes (e.g., MGMT methylation, EZH2 amplification) that predict resistance." (PMID 41234540, 2025). "The differential response to EZH2 inhibitors between HB and HCC cells further underscores the need for tumor-specific therapeutic strategies." (PMID 40766612, 2025). "In our study, we observed a significant upregulation of Ezh2 following TPA and mezerein exposure, suggesting a potential epigenetic mechanism contributing to tumour transformation in Bhas42 cells." (PMID 40182023, 2025). "Our analysis suggested LURAP1L-AS1 to act as a molecular sponge for miR-7a-5p, miR-101-3p, miR-181a-5p, and miR-27a-3p, resulting in the upregulation of EZH2, MCL1, and KRAS, among other tumor promoting." (PMID 39995981, 2025). "EZH2, AURKB, GPC3, CTNNB1, and TGFβ were significantly upregulated in tumor tissues, indicating their potential roles in tumor progression." (PMID 40766612, 2025). "Another promising compound, UNC1999, targets both EZH1 and EZH2 to reduce H3K27me3 at the SLFN11 promoter, thereby sensitizing HCC cells to sorafenib and enhancing anti-tumor effects." (PMID 40057667, 2025). "Abnormally expressed NCAPD3 in prostate cancer caused STAT3 to be highly expressed and bound to the promoters of JAK2 and EZH2 to promote their transcription, increasing the level of AKT phosphorylation, and accelerating tumor development." (PMID 39917394, 2025). "Combined chemical inhibition of EZH2 and PI3K/mTORC1 resulted in superior anti-tumor activity in murine and human phenotypic plastic models and was most significant when this combination was used with castration or enzalutamide." (PMID 40832297, 2025). "EZH2 functions as an inhibitor of CD4+ and CD8+ effector T-cell recruitment into the tumor microenvironment in pcALCL, favoring immune evasion, tumor progression and antitumor immunity, making it an interesting pharmacological target." (PMID 40565334, 2025). "Epigenetic drugs, such as EZH2 inhibitors, can reduce Treg suppressive activity and reprogram the TME to support anti-tumor immunity." (PMID 40739089, 2025).
tumor (continued). "Consistently, pharmacological inhibition of EZH2 reduces H3K27me3, upregulates NEUROD1, and drives tumor cell differentiation, thereby inhibiting tumor growth." (PMID 40599851, 2025). "Silencing EZH2 in CNDT2.5 cells reduced proliferation and induced apoptosis, while EZH2 knockout in a xenograft model inhibited tumor growth." (PMID 41458541, 2025). "EZH2, PCNA, and BIRC5 were predominantly expressed in epithelial clusters, supporting their tumor-intrinsic roles." (PMID 40678068, 2025). "For example, persistent IL-6/STAT3 signaling within the tumor microenvironment induces DNMT1 and EZH2 expression, thereby reinforcing the epigenetic repression of tumor suppressor genes and maintaining a pro-oncogenic inflammatory state." (PMID 41226277, 2025). "EZH2 (Enhancer of Zeste Homolog 2) promoted PDAC progression and de-differentiation by increasing tumor cell invasion and suppressing differentiation pathways." (PMID 40699746, 2025). "Moreover, double positivity for H3K27me3 and EZH2 could portend a poor prognosis for this tumor." (PMID 39636550, 2025). "Conversely, targeted deletion of Usp22 resulted in enhanced EZH2 ubiquitination both RM1 and MC38 tumor cells." (PMID 41252204, 2025). "By targeting SLC31A1‐mediated copper influx and EZH2‐driven immunosuppression, our findings support repurposing copper chelators (e.g., TEPA) or developing SLC31A1 inhibitors to disrupt tumor‐intrinsic copper addiction." (PMID 40719074, 2025). "EZH2 also plays a role in the activation of STAT3 signaling, which is involved in tumor cell migration, invasion, and angiogenesis." (PMID 39858107, 2025). "Aberrant expression of EZH2 correlates with unfavorable prognosis in several cancers by promoting epithelial-mesenchymal transition (EMT), tumor progression, and metastasis 17-20." (PMID 41209556, 2025). "C-Myc induces PIM1, a serine/threonine kinase, and EZH2, a member of PRC2 polycomb repressor complex, by repressing mir26a to promote tumor proliferation and invasion." (PMID 40044981, 2025). "In cervical cancer, ANLN activates EZH2 to drive EMT and inhibit apoptosis, thereby enhancing tumor cell migration." (PMID 41573677, 2025). "Nevertheless, MYCN was found to downregulate DPYSL3, possibly through the action of the enhancer of zeste homolog 2 (EZH2), which methylates histones of tumour suppressor genes." (PMID 38542729, 2024). "To understand the tumor-cell intrinsic effects of EZH2 inhibition, we treated four different NSCLC cell lines with the EZH2 inhibitors GSK126 or EPZ6438 for 5 days, followed by 2 days of EZH2 inhibition with IFNγ." (PMID 38265267, 2024). "Remarkably, overexpression of EZH2 has been identified in various cancers, including HCC, where it exhibits a positive correlation with tumor malignancy." (PMID 39516467, 2024). "Of note, the expression of pTyr397FAK, N-methyltransferase enzyme (EZH2) and tri-methylation of the H3K27 residue correlated with tumor size and alpha-fetoprotein (AFP) levels." (PMID 38947885, 2024). "We also assessed the SIRT7, EZH2, and RND3 protein levels in tumor tissues from each group of mice using IHC." (PMID 39719443, 2024). "In SCLC-resistant xenograft mouse models, the EZH2 inhibitor EPZ011989 restores tumor sensitivity to irinotecan by upregulating SLFN11, and its combination with irinotecan significantly inhibits tumor growth." (PMID 38525426, 2024). "The tumor microenvironment of CDX-grafted mice with the three HCMV GB and DB strains was assessed for Myc and EZH2 gene expression." (PMID 38553638, 2024). "Among the genes identified as significantly upregulated or downregulated in SNUC, EZH2 and the histone family gene, such as H3C2 (H3 clustered histone 2), were notably upregulated in SNUC tumor cells (fold change > 1.5 times, p < 0.05)." (PMID 39565059, 2024).
tumor (continued). "In future in vivo experiments, the combined inhibition of EZH2 and CCL22-CCR4 will be employed to investigate alterations in tumor proliferation, apoptosis and metastasis." (PMID 39513112, 2024). "Combination therapy with 2‐ME2 and EPZ6438 demonstrated promising antitumor activity in an in vivo A549 xenograft tumor model, suggesting that dual targeting of HIF‐1α and EZH2 is an emerging and attractive therapeutic approach." (PMID 38072662, 2024). "MYC, EZH2 and CTNNB1 were the primary stemness genes with high expression levels in C2 UBE2C+ tumour cells." (PMID 38894657, 2024). "In contrast, treatment of mice with the EZH2 inhibitor GSK126 showed excellent tumor control with some tumor regression, and treatment with EZH2 inhibitor and anti-PD1 lead to significant tumor regression in all mice tested." (PMID 38265267, 2024). "EZH2, frequently overexpressed in various cancers including HCC, has been investigated to mediate tumor suppression upon its inhibition through diverse pathways." (PMID 39516467, 2024). "Zeste homology 2 (EZH2), the catalytic subunit of PRC2 provokes the release of LOXL4 in tumor cells to modulate the activation of macrophage into TAMs via miR-29b/miR-30d-LOXL4 axis in TNBC." (PMID 38715072, 2024). "This study suggests that expression of EZH2 in adult acinar cells restricts PDAC initiation and progression by affecting both the tumor microenvironment and acinar cell differentiation." (PMID 39739419, 2024). "The identified epigenetic PARPi hallmarks contained hundreds of DMRs; however, only a few DMRs were reported as tumor driver genes (SOX2, POU2AF1, PTK6, VHL, JAK3, and EZH2) or as HRD genes (RAD51C)." (PMID 38927686, 2024). "Spatial transcriptome analysis revealed notable upregulation of EZH2 and the histone family gene such as H3C2 (H3‐clustered histone 2) in SNUC tumor cells." (PMID 39565059, 2024). "In metastatic prostate cancers, EZH2 represses IFNGR1 expression in a Myc-dependent manner, impairing interferon (IFN) signaling, which is crucial for anti-tumor immunity." (PMID 38534385, 2024). "We observed significant tumor control in both the anti-PD1 with EZH2 inhibitor combination, as well as EZH2 inhibition alone." (PMID 38265267, 2024). "We examined the tumor cell proliferation in ATLL by assessing Ki-67 nuclear staining, and correlated Ki-67 staining with EZH2 expression." (PMID 38339397, 2024). "These compounds exhibit potent and selective inhibition of both EZH2 and EZH1, effectively reducing H3K27me3 levels, and have demonstrated significant anti-tumor activity against diffuse large B-cell lymphoma cells with gain-of-function mutations." (PMID 39620228, 2024). "We performed the ESTIMATE analysis to evaluate tumor immune infiltration and tumor purity, and the result showed the immune score and ESTIMATE score were significantly higher in patients with high EZH2." (PMID 38882008, 2024). "DNA methyltransferases (DNMTs), histone deacetylases (HDACs), EZH2, bromodomain protein 4 (BRD4), and lysine-specific histone demethylase 1A (LSD1), which play important roles in tumor biology, have also been shown to regulate anti-tumor immunity as well." (PMID 38275900, 2024). "Under chemotherapy induction, EZH2-mediated H3K27me3 deposition in the SLFN11 gene body suppresses SLFN11 expression, thereby enhancing DNA repair efficiency, enabling tumor cell adaptation and survival." (PMID 38525426, 2024). "While there is no recurrent gene amplification that was observed, the following genes were amplified in two tumor samples: MET, SMO, ERBB2, BRAF, EZH2, SRSF2, CUX1, and CEBPA." (PMID 38164123, 2024). "These include lower expression of enhancer of zeste homolog 2 (EZH2) and lower neutrophil-to-lymphocyte ratio (NLR) in younger patients, reflecting lower invasion and metastasis of the tumor behavior in this age group." (PMID 39830511, 2024).